MYC (MYC proto-oncogene, bHLH transcription factor)
Diseases named in the same sentence as MYC in open-access papers (continued):
Sharing a sentence is not in itself a finding about the gene and the disease.
cancer (continued). "The compound was found to significantly reduce the expression of MYC and to exert an anti-cancer activity in a panel of cancer cells as well as in multicellular tumor spheroid models." (PMID 34073075, 2021). "An increased level of c-MYC expression has been observed in many different types of cancer, including HNSCC cancers." (PMID 34204834, 2021). "According to previous reports, among 33 different cancers, MYC amplification was found in 21% of patients, especially BRCA, UCEC, and OV." (PMID 34631699, 2021). "A STRING protein–protein interaction analysis further revealed that AKT and MYC are hub proteins for cancer progression." (PMID 34944720, 2021). "MYC directly activates the TFRC gene to serve the iron demands of aggressive cancers, allowing to indirectly image its activity." (PMID 34637026, 2021). "Selectively targeting CDK7 has been proven as a useful therapy for cancers that are driven by MYC amplification." (PMID 33889549, 2021). "Small molecules can bind to the MYC promoter G4 to down-regulate MYC transcription and induce cancer cell death." (PMID 33978746, 2021). "The common TMPRSS2 and FURIN associated genes CTSL, MYC, AKT1, and SRC displayed positive correlations with their corresponding subjects except for the FURIN and MYC correlation in cancers (R 0.012; p 0.199)." (PMID 33796097, 2021). "All three aurora kinases, AURKA-C, serve oncogenic roles in cancer by promoting cell cycle progression, cancer cell survival, and promoting MYC/MYCN expression and activity." (PMID 33829040, 2021). "A clinical trial for the highly selective CDK9 inhibitor KB-0742 was even launched recently in January 2021 to treat MYC-amplified cancers and is currently enrolling patients with advanced solid tumors or non-Hodgkin’s lymphoma." (PMID 34207158, 2021). "As a single clonal cancer population, we assumed all cells were initially in a doxycycline-sensitive MYC-On state (blue curve)." (PMID 33446671, 2021). "Studies have shown that MYC facilitates the anabolism of cancer cells by modulating the expression of multiple metabolic enzyme genes, such as GLUT1, PKM2, and LDHA." (PMID 33889549, 2021). "Other cancer amplified genes that also significantly increase ARE reporter activity are MYC (a previously known gene to exert post-transcriptional effect), MYCN, CCND1, CCNE1, SKP2, and NOTCH2." (PMID 34535639, 2021). "Although the combined evidence for the role of MYC in cancer is compelling, the mechanisms by which high levels of MYC drive tumourigenesis are more contentious." (PMID 33799592, 2021). "The master transcriptional regulator MYC proto-oncogene (MYC) is deregulated in >50% of human cancers, in line with a central function in controlling a multitude of oncogenic processes including differentiation, proliferation, and apoptosis." (PMID 34337362, 2021). "The MYC oncogene, a transcription factor, has become of growing interest as a fundamental driver of differential cancer cell metabolism." (PMID 34503295, 2021). "The overexpression of SLC1A5 (also known ASCT2), a sodium-dependent transporter for neutral amino acids with high affinity for Gln, is highly expressed in several cancer types, especially those with MYC overexpression." (PMID 34445444, 2021). "This study suggests that UBR5-mediated MYC ubiquitination and degradation prevents the accumulation of too much MYC and thus benefits cancer cell survival." (PMID 34178666, 2021). "MYC is a driver oncogene that is overexpressed in a wide range of human cancers, including hematopoietic, breast, liver, colon, ovarian, lung carcinomas, osteosarcomas, glioblastomas, melanoma and myeloid leukemias." (PMID 33446671, 2021). "Previous evidence also suggests that c-MYC activates the expression of HNRNPs to maintain a high PKM2/PKM1 ratio in cancer cells." (PMID 34887764, 2021). "Responses in patients with NC, other solid tumours and DLBCL provide proof-of-principle for BET inhibition in MYC-driven cancers." (PMID 33311588, 2021).
cancer (continued). "The MYC oncogene is a central player in the majority of human tumors and is a general amplifier of transcription in cancers." (PMID 33978746, 2021). "As they are central for many cancers, MYC ENHs represent one of the best examples of plasticity and cooperation." (PMID 34680347, 2021). "The possibility of using miRNA complementary to the MYC gene sequence is being considered as a targeted therapy for cancer." (PMID 34440124, 2021). "Nevertheless, this less studied F-box protein functions to promote cancer cell growth and potentiates MYC oncogenic activity." (PMID 34178666, 2021). "Using gene set enrichment analysis (GSEA), we observed a signature of multiple cancer signaling pathways, including MYC and E2F, known to drive cell proliferation." (PMID 34326322, 2021). "MYC, a prominent gene in MYC targets v1 gene set, is common in aggressive tumors and contributes to cancer development." (PMID 34567213, 2021). "KEGG analysis demonstrated that these genes are involved in several cancer-related pathways, and GSEA identified 8 hallmark pathways, including MTORC1, MYC targets, DNA repair, G2M checkpoint signaling." (PMID 33391414, 2021). "One application of this is the gene expression changes in human cancer cells induced by overexpression of the oncogene MYC, which has been suggested to play an amplifier role to drive small increases in all expressed transcripts, but this effect is debated." (PMID 33720010, 2021). "We utilized both model cell lines and human cancer cell lines to confirm the MYC-diMF synthetic lethal interaction." (PMID 33760847, 2021). "USP28 is a targetable DUB enzyme that stabilizes crucial oncoproteins in cancer, such as the transcription factor c-MYC." (PMID 34685632, 2021). "Proteins such as c-MYC and HIF1α are frequently stabilized and/or upregulated whereas, in the same way, lncRNAs alter signaling pathways favoring cancer progression." (PMID 33652661, 2021). "The MYC:TRRAP interaction is a MYC vulnerability in cancer and presents an opportunity for drug discovery." (PMID 34676047, 2021). "Deletion of each one of these elements led to a strong effect on MYC expression and on cancer cell proliferation, indicating that each of these seven interspersed ENHs is required to sustain MYC’s robust expression in this setting." (PMID 34680347, 2021). "FUBP1 overexpression was found in many cancers and led to a dysregulation of targets including MYC oncogene." (PMID 34116677, 2021). "Several known potent oncogenes that regulate CDKN2B-AS1 expression in various cancers have been reported in the literature, including MYC, RELA, and ERBB2." (PMID 33849428, 2021). "As MYC is a difficult therapeutic target, increasing our knowledge of other proteins in the MYC network will provide the basis for alternative strategies to impair MYC activity in cancer." (PMID 34572909, 2021). "c-MYC is a transcription factor that orchestrates a potent pro-cancer programme across multiple cellular pathways." (PMID 34636321, 2021). "Based on the presented evidence, we believe that one of the mechanisms by which autophagy provides cytoprotective effects in ALK+ ALCL cells is related to its induction/maintenance of cancer stemness, which correlates with a high protein level of MYC." (PMID 34685497, 2021). "Recently, Omomyc, a peptide that competitively binds to E-box elements as a heterodimer with MAX or as a homodimer and suppresses the binding of MYC to E-boxes, has been shown to have therapeutic potential in vivo in various cancer models." (PMID 34178666, 2021). "In other words, the components of the spliceosome are closely related to aggressive MYC-driven cancers and can be used as therapeutic targets." (PMID 33928086, 2021).
cancer (continued). "For example, the c-MYC protein, which is dysregulated in several cancers, is coded by a gene that contains a G-rich promoter element that forms G4s." (PMID 34299488, 2021). "Further analysis of CNV in 8q24.2 at genetic resolution revealed that amplifications of the oncogenes located on this fragment, MYC and NDRG1, were also associated with HRD in a pan-cancer manner." (PMID 34976815, 2021). "FOXK1, like MYC, regulates several biological processes related to cancer initiation, development, metastasis, angiogenesis, and drug resistance, explaining the importance of deregulated FOXK1 in various types of cancers." (PMID 34689785, 2021). "ZEB is the important transcription factor mediating the EMT process of human cancer cells; c-MYC not only promotes the proliferation of cancer cells, it also participates in the aberrant metabolism of cancer cells." (PMID 34249768, 2021). "c-MYC deregulation reprograms gene expression and promotes uncontrolled cell proliferation – one of the hallmarks of cancer." (PMID 33718147, 2021). "Studies have shown that MYC gene products, especially c-myc, play a key role in the occurrence and development of cancer." (PMID 34744739, 2021). "For example, MYC is an oncogene in many cancers and plays an important role in regulating metabolic pathways, especially glutamine and glutamine breakdown." (PMID 34859058, 2021). "MNT is a crucial modulator of MYC, controls several cellular functions, and is activated in most human cancers." (PMID 34572909, 2021). "Although the role of MYC in driving glycolysis and cancer progression is well documented, it has yet to be successfully targeted for therapeutic benefit." (PMID 34556188, 2021). "This renders cancer cells with deregulated MYC particularly sensitive to inhibitors of such pathways." (PMID 34637026, 2021). "As MYC regulates all active promoters and enhancers in the cancer genome, it would be desirable to identify the key metabolic enzyme(s) responsible for the global metabolic alteration associated with OS development." (PMID 33400690, 2021). "Taken together, these observations suggest that increased expression of c‐MYC and/or G9a helps cancer cells to increase cellular iron availability by increasing iron influx while at the same time reducing its storage and release." (PMID 34551213, 2021). "It is noteworthy that increased and differential MYC expression was observed in tumors of relevant clinical cancer datasets." (PMID 33859744, 2021). "PVT1 depletion can induce apoptotic cell death of cancer cells, whereas MYC silencing does not affect cell death, suggesting different mechanisms of PVT1 and MYC function in different cancers." (PMID 33435206, 2021). "Cells that overexpress MYC bypass these mechanisms, acquiring many “hallmarks” of cancer, most notably unlimited and uncontrolled cell proliferation." (PMID 33801599, 2021). "MYC contributes to the genesis of many cancers and although it has been a focus of drug research, strategies to target or exploit MYC have yet to be clinically successful." (PMID 33760847, 2021). "In cancer cells with low MYC levels, MYC co-occupies with RNA pol II promotor regions of actively transcribed genes." (PMID 33801599, 2021). "For example, in MYC-driven cancers, targeting of certain glycolytic enzymes upregulated by MYC represented vulnerabilities that are not present in cells with non-dysregulated levels of MYC and are potentially targetable for treatment." (PMID 34066504, 2021). "Small-molecule stabilizers of the c-MYC i-motif that decrease expression of this key oncogene have immense utility as new agents for cancer treatment especially given that the c-MYC protein is considered undruggable." (PMID 33513764, 2021). "MYC induces SREBP1c-dependent de novo FA synthesis and directly activates the transcription of key lipogenic enzymes to support cancer growth." (PMID 34183658, 2021).
cancer (continued). "MYC target pathways were found to be downregulated in AD and PD and upregulated in most of the studied cancers." (PMID 34203763, 2021). "In particular, therapeutically targeting SKP2, which is overexpressed in a variety of cancers, has exciting potential to capitalize on MYC’s pro-apoptotic function." (PMID 34178666, 2021). "(iii) MYC:MYC is one of the oncogenes that is activated and contributes to many aspects of human cancer." (PMID 34944772, 2021). "With regard to their broad impact in cancer, our findings contribute to explain the pleiotropic functions of curcumin, and suggest that this natural spice, or more bioavailable derivatives thereof, may constitute useful adjuvants in the therapy of MYC-dependent and TRRAP-associated human tumors." (PMID 33937075, 2021). "This experiment strongly suggests that combined inhibition of CDK9 and BRD4 would be a useful strategy to combat cancers, which show high levels of MYC or other genes, whose expression is regulated by super-enhancers." (PMID 34359807, 2021). "Important cancer-related molecules were observed as potential regulators for the DEPs, such as MYC, CD3, CEBPB, PI3K complex, SMARCA4 and the anti-cancer chemical drugs 5-fluorouracil, dexamethasone, sirolimus (rapamycin) and tretinoin." (PMID 33656060, 2021). "Plasmacytoma variant translocation 1 (PVT1) is a long non-coding RNA (lncRNA) that functions as an oncogene in many cancers and is known to promote MYC expression in I-BET151-resistant AML cells in a BRD4-independent manner." (PMID 34540687, 2021). "In cancer, the genetic deregulation of MYC expression drives malignant transformation and is implicated in hepatocarcinogenesis." (PMID 34663798, 2021). "Cases with MYC gain and PTEN loss were also more likely to have cribriform Gleason pattern 4 carcinoma (>200 μm) at biopsy by logistic regression (OR, 8.85; 95% CI, 2.96–27.82; P = 0.0001 for combined PTEN loss and MYC gain)." (PMID 34062284, 2021). "These clinical findings are supported by experimental data showing that MYC acts as a biomarker of the anti-cancer action of HDACI romidepsin and entinostat in DLBCL." (PMID 33097085, 2020). "MYC, also known as MYCC and c-Myc, is frequently amplified in numerous human cancers via transcriptional regulation of specific target genes, including miRNA and lncRNA." (PMID 32102656, 2020). "Not surprisingly, given MYC’s capacity to promote programs of proliferative cell growth, MYC is frequently upregulated in cancer." (PMID 33092025, 2020). "Currently, the principal clinical approach towards targeted therapies mitigating high MYC expression in cancer has focused on BET bromodomain inhibition." (PMID 32331235, 2020). "Important regulators of cancer stem cell characteristics particularly include the members of the MYC transcription factor family, consisting of L-, N-, and CMYC." (PMID 32927768, 2020). "As previously reported, lncRNA CCAT2 promotes cancer progression by increasing MYC gene expression in cancer cells." (PMID 32230936, 2020). "Overall, mitochondrial function is promoted by MYC, allowing cancer cells to proliferate in oxygen and nutrient sufficient conditions." (PMID 33251216, 2020). "Focusing on the TCGA pan-cancer study, which includes data from 33 cancer types, we first observed the CNV and mutational profiles of the tumor suppressor RB1, the proto-oncogene MYC, and the translation initiation factor EIF4E." (PMID 33266490, 2020). "It is noteworthy that different transcriptional pathways such as c-MYC oncogenic transcription, hormone receptors and nutrient starvation responses regulate the expression of amino acid transporters in human cancers." (PMID 32200487, 2020). "Reductions in p-eIF4E level with a MNK1/2 inhibitor reduced the expression of PD-L1 in a MYC/KRAS model of cancer." (PMID 32759815, 2020).
cancer (continued). "MYC-driven immune evasion is the collective effort of cancer and other cells present in TME—of which TAMs are the most important ones." (PMID 33081056, 2020). "Its amplification and overexpression have been described as main events, by which MYC is deregulated in various cancer entities." (PMID 33298978, 2020). "For example, VPS9D1-AS1, a known Wnt/MYC target, was both Wnt-activated in our study and also upregulated in 11 different types of cancers, consistent with its established role as a lncRNA with oncogenic function." (PMID 33092630, 2020). "Differences in MYC levels have also been suggested to induce cell competition in human cancer cells." (PMID 31102668, 2020). "Alternatively, ERK activation is associated with an increase in c-MYC protein levels and its transcriptional activity, as well as an increase in VEGF levels in several cancer models." (PMID 33081077, 2020). "While it is well-established that MYC protein is overexpressed in cancer, how post-translational modifications of MYC contribute to altered functions of MYC in the development, progression, and metastasis of SCC has not been reported." (PMID 32895364, 2020). "Members of RAS and MYC families of proteins are cooperating oncogenes, and their interplay and interdependency in driving cancer development and maintenance are well-established phenomena." (PMID 32610656, 2020). "While the ER constitutes a link between these intracellular processes and the changes in cellular biomass and growth, it has been underappreciated in the context of MYC‐hyperactivated cancers until recently." (PMID 32310340, 2020). "As a transcriptional factor, c-MYC is regarded as a human proto-oncogene and leads to multiple features of cancer." (PMID 32962742, 2020). "There is evidence that differentiation therapy using ATRA involves MYC/NMYC regulation in cancer cells." (PMID 32927768, 2020). "Correspondingly, MYC and AR are the other regulators, down-regulated when the cells are transformed into cancer cells." (PMID 32193399, 2020). "Extensive efforts to develop small molecules that bind and stabilize the MYC G4 have unlocked a potential method for targeting MYC driven cancers." (PMID 33066043, 2020). "Cancer cells adapt to hypoxia by overexpressing c-MYC, which stimulates glycolysis and cell proliferation via ENO1 upregulation and MBP-1 downregulation." (PMID 33584813, 2020). "There are no integration sites in chromosomes 21, 22, and X. Only five genes of the many associated with MCPyV integration, namely SF3B1, TLX3, CD74, MYC, and KMT2D, are cancer-linked genes listed in the COSMIC database." (PMID 32878339, 2020). "As elevated MYC is seen in almost all types of cancers, neoplastic cells must defeat whatever safeguards enforce physiological MYC levels." (PMID 33005010, 2020). "Inhibiting the spliceosome function in cancer cells can effectively suppress malignant cancers driven by the MYC." (PMID 33064752, 2020). "The c-MYC gene is known to be one of the most frequently deregulated oncogenes and a driver for many human cancers." (PMID 33134177, 2020). "The abrogation of MYC-potentiated apoptosis is a crucial event of cellular transformation and cancer progression." (PMID 32549409, 2020). "Here we show that DZNep reduces Otx2/c-MYC cancer cells growth ex vivo highlighting a possible therapeutic function of EZH2 inhibition." (PMID 31996670, 2020). "MYC, whose deregulation has been found in most cancers including CRC, has a pivotal role to play in the tumorigenesis and carcinogenesis of CRC via the Wnt/β-catenin pathway." (PMID 33183350, 2020). "Since amplification of c-MYC plays a key role in cancer progression and proliferation and is common in OCCC it is a potential treatment target." (PMID 33088426, 2020).